IL10 (interleukin 10)
Diseases named in the same sentence as IL10 in open-access papers (continued):
Sharing a sentence is not in itself a finding about the gene and the disease.
infection (continued). "IL-12/IL-10 interaction is the line of balance in kala-azar: at the infection site, intracellular amastigote molecules drive the activity of the infected macrophages to promote a predominant IL-12/ IFN-γ or IL-10/IL-27 synthesis." (PMID 40732663, 2025). "In fact, in IPA, IL-10 signaling emerged as one of the top downregulated pathways in bystander cells in ADE conditions compared to those in conventional infection." (PMID 39902963, 2025). "The concentration of chemokines CxCL1/KC/GRO-α, CxCL2/MIP-2, CCL5/RANTES and cytokines TNF-α, IL-1β, IFN-γ, IL-5, IL-6, IL-9, IL-10, IL-13, IL-17, IL-23 circulating in blood were measured in experimental animals on day 15 post-infection." (PMID 40445994, 2025). "IL‐10 producing B cells have been identified in male only infections and in mixed‐sex infections, but the effect of female only secretions on immune cells has not been reported." (PMID 40916477, 2025). "We additionally show that atRA correlates with some inflammatory cytokines across infection types, including IL‐1β, IL‐6, IL‐10 and IL‐12." (PMID 40031928, 2025). "IL-10 is a key anti-inflammatory cytokine, whereas IL-17 is a pro-inflammatory cytokine involved in the recruitment of immune cells to sites of infection." (PMID 39885417, 2025). "While there was a slight increase in IL-15 secretion (5 ± 2 vs. 8 ± 3 pg/mL) and IL-10 (1.4 ± 2.0 vs. 2.3 ± 2.5 pg/mL) upon infection, IL-8 and IL-1β remained unchanged." (PMID 41239423, 2025). "It has previously been shown that B cells are a source of IL-10 during Mtb HN878 infection in female mice." (PMID 40260245, 2025). "The expression of IL-1β, IFN-α2, IFN-γ, TNF-α, MCP-1 (CCL2), IL-6, IL-8 (CXCL8), IL-10, IL-12p70, IL-17A, IL-18, IL-23, and IL-33 was assessed in apical washes at different time points after infection using a 13-plex immunoassay." (PMID 40143308, 2025). "In our study, infection led to an early increase in IL-10 serum levels, consistent with previous reports detecting IL-10 in both serum and lung tissue." (PMID 41150385, 2025). "For example, mast cells (MCs) can produce IL-10 under specific stimulation (such as IgE cross-linking, IL-33, or pathogen infection)." (PMID 41300695, 2025). "Apoptotic markers (caspase-3, Bax, Bcl-2) were analyzed by immunofluorescence and immune genes expression kinetics (TLR3/7, RIGI, MDA5, IL-1β, IL-6, TNFα, IL-10, IFNβ and β-catenin) were measured at defined time points post-infection by RT-qPCR." (PMID 41157617, 2025). "HCMV IL-10 viral proteins can potentially impact the immunosuppression of the host in different phases of infection." (PMID 40284944, 2025). "On the other hand, the expression of the anti-inflammatory cytokine IL-10 was significantly increased in animals with amoxicillin-induced dysbiosis and infection (AMOX + BCG) compared to the other groups." (PMID 40009606, 2025). "The analysis of the surviving rainbow trout after the bath challenges indicated that genes associated with immune markers, such as CD4, IL-1β, IL-10 and TNF-α, showed minimal response (in gene regulation) to infections caused by P. salmonis." (PMID 41334221, 2025). "To investigate this finding in the context of M. avium, we assessed IL-10 levels in the culture supernatants following an infection." (PMID 40391046, 2025). "Conversely, low levels of IL-10, the core anti-inflammatory cytokine of Treg cells, reflect impaired immune regulatory capacity, making it difficult to control the post-infection cytokine storm." (PMID 41425878, 2025). "Hp-related VacA activates MC by promoting the secretion of TNF-α, IL-6, and IL-10 and engaging chemokine receptors to attract additional immune cells to the site of infection." (PMID 40871387, 2025). "As a key immunosuppressive cytokine, IL-10 acts on leukocytes to resolve infections and inflammation, with functions including reducing tissue injury, inhibiting antigen-presenting cell function, and promoting the survival and function of regulatory T cells." (PMID 41300695, 2025).
infection (continued). "Key cytokines such as interleukin-6 (IL-6), interleukin-8 (IL-8), and interleukin-10 (IL-10) are frequently studied for their roles in inflammation and infection." (PMID 40137168, 2025). "The LSDV005 gene is expressed in the early stages of infection and acts like cellular interleukin-10 (IL10), influencing the formation of the immune response." (PMID 41157660, 2025). "Offspring of both LFD- and HFD-fed dams exhibited reduced basal levels of key cytokines, including IL-6, IL-10, G-CSF, and GM-CSF, indicating a dampened innate immune system prior to infection." (PMID 40766470, 2025). "These cytokines are typically released early during infection to initiate inflammation, with IL-10 acting to balance their effects." (PMID 40406273, 2025). "Infections with L. amazonensis are characterized by a high parasite burden at site of infection, elevated IL-10 production, and an impaired cellular immune response." (PMID 39775223, 2025). "We used Luminex profiling of serum taken at 6 days post infection in the high dose cohort to analyse the relative levels of 9 cytokines and chemokines: IL-1α, IL-1ß, IL-6, IL-10, IL-12(p70), IL-17, CCL2/MCP-1, GM-CSF and IFN-γ." (PMID 40587585, 2025). "Elevated il8 and il10 expressions reflect improved immune regulation, with il8 recruiting immune cells to infection sites and il10 controlling inflammation to prevent immune overactivation." (PMID 40564266, 2025). "Our results for IL-10 are consistent with prior studies suggesting this cytokine plays a role in augmenting immunosenescence and increased vulnerability to infection in later life." (PMID 41280118, 2025). "In contrast, anti-inflammatory cytokine transcription in TCR Cγ−/− chickens was increased in the early infection phase (IL-10) and during the later stage (TGFβ) of immune regulation." (PMID 40438105, 2025). "Blocking early TGF-β production during Py17XL infection triggers a rise in IL-10 while simultaneously blocking both TGF-β and IL-10R signalling increases TNF-α and IFN-γ levels, allowing prolonged survival and infection resolution in 40% of these mice." (PMID 39907835, 2025). "Elevated levels of IL-10 (3.2 times) were also detected, suggesting that the tissue had established a dual pro- and anti-inflammatory response cascade at this post-infection time." (PMID 41474758, 2025). "The levels of IL-12p40 and IL-10 were quantified to assess the impact of Rv1899c on cytokine modulation during infection." (PMID 41303360, 2025). "Probiotics also have a negative effect on biofilm formation and modulate the host cell immune response to infection by influencing the balance of pro- and anti-inflammatory cytokines (e.g., IL-8, IL-10, TNFα, IL-1β, and IL-4)." (PMID 41009849, 2025). "During infections with extracellular or highly inflammatory bacteria, IL-10 production is needed for host survival." (PMID 41425551, 2025). "The cytokines TGF-β, INF-γ, and IL-10 were increased during infection and decreased following therapy." (PMID 40377774, 2025). "The study found that polymorphisms in the TLR4 gene (rs4986790), IL-10 gene (rs1800896), TNF-α gene (rs1800629), and MBL2 gene (rs1800450) were significantly associated with patients’ susceptibility to infection, disease severity, and prognosis." (PMID 40692949, 2025). "A pronounced, infection-dependent increase in the expression levels of TNF, IL-8, and IL-10 was observed over the course of infection, with the most substantial upregulation occurring at the earliest time point." (PMID 40794782, 2025). "Following infection, these cells release chemokines like IL-1β and IL-10, which promote the differentiation of naive CD4+ T cells towards the Th17 lineage while suppressing the differentiation and function of Treg cells." (PMID 41425878, 2025). "We analyzed levels of cytokines at the site of infection including IFNγ, IL-10, IL-17, IL-4, and IL-13 by quantitative real-time PCR." (PMID 40655011, 2025).
infection (continued). "Both mouse strains exhibited low levels of IL-6 and IL-10 following infection with the icmQ::Tn mutant, which is consistent with the rapid clearance of this mutant by the immune system." (PMID 40586810, 2025). "In SCAT of aged mice, infection induced an increase in Il10 levels at 4 and 7 dpi, Tnfa at 4 dpi, and both Il1b and Il6 at 7 dpi." (PMID 41145556, 2025). "In contrast, IL10 levels were significantly increased in both blood and peritoneal fluid prior to infection at day 0, and PI3KCDGOF/B mutants also mounted stronger IL10 responses at day 4 and 7 post-infection." (PMID 41191641, 2025). "Except for il10, all innate immune-related genes showed dynamic changes in the head-kidney during the post-infection period." (PMID 41256851, 2025). "In the lymph nodes, we observed significant increases in the levels of IL-4, IL-6, TNF, and IFN-γ at 22 days after infection and increases in the levels of IL-2, IL-1, and IL-10 in infected mice at 35 days." (PMID 39899646, 2025). "Cytokine profiling of macrophages post-infection revealed that CB1R-KO mice had reduced IL-10 levels, along with increased IL-6 and TGF-β, suggesting a dysregulated polarization state that combines pro-inflammatory and regulatory elements." (PMID 40161677, 2025). "Inhibition of LAP resulted in the decrease of interleukin (IL)-10 secretion and the restoration of the autophagy flux, suggesting that modulation of autophagy during infection alters immune response and promote persistence." (PMID 40395986, 2025). "We showed that anti-inflammatory cytokine Interleukin (IL)-10 and immune-modulatory granulocyte macrophage colony-stimulating factor (GM-CSF) were significantly upregulated after infection with rCDC-9 P45 compared to rCDC-9 P11." (PMID 41060027, 2025). "This suggests a complex regulation of immune responses where IL-10 moderates’ inflammation to prevent tissue damage while allowing sufficient pro-inflammatory activity to combat the infection." (PMID 40446677, 2025). "IL-10 was unchanged in neonates with infection but was significantly upregulated in adults following HMPV infection." (PMID 40280180, 2025). "In this study, TNF, IL-10 and IL-8 showed an infection-dependent induction, with strong secretion at early time points but, surprisingly, without significant sex-specific differences." (PMID 40794782, 2025). "During the natural course of a S. molnari model infection, the first suppression of the proinflammatory response occurs after approximately 28 days, which corresponds to a peak in il10 expression." (PMID 40391212, 2025). "It is noteworthy that, 48 h post-infection, there was a sharp decrease in IL-4 levels, an increase in IL-10, and a reduction in IL-12 induced by CM, highlighting, therefore, the ability of this molecule to balance the Th1 and Th2 responses." (PMID 40299671, 2025). "FHA promotes IL‐10 production by dendritic cells (DCs) and macrophages and directs naïve T cells to differentiate into IL‐10‐secreting regulatory type‐1 (Tr1) cells during infection with B. pertussis." (PMID 40629997, 2025). "This would explain the slight decrease in TNF-α expression as the infection progressed and the increase in IL-10 in infected animals." (PMID 40743218, 2025). "Up-regulation of IL-10 is beneficial in the early phase of infection because it limits the extent of the immune response, prevents excessive inflammation and immune-mediated damage, and allows inflammation resolution after pathogen elimination." (PMID 41003928, 2025). "Various cell signaling cytokines such as tumor necrosis factor-alpha (TNF-alpha), interferon-gamma (IFN-gamma), interleukin-6 (IL-6), and interleukin-10 (IL-10) are activated during infection, facilitating immune cell differentiation." (PMID 40086236, 2025). "Consistently, the LASSO regression retained five of these six parameters as the strongest predictors of infection status: urea (coefficient = 0.41), IL-10 (0.53), TNF (0.49), CCL3 (0.38), and IL-1β (0.33)." (PMID 41279035, 2025).
infection (continued). "Still, because the induction of M2-associated cytokine secretion by microbes has been described as a common mechanism to suppress inflammatory responses, we tested levels of secreted IL-10, an immunosuppressive cytokine, across infection conditions." (PMID 40996031, 2025). "The emergence of immunosuppressive IL-10 responses corresponded to the emergence of MDSC-like cells during the time-course of infection." (PMID 41415274, 2025). "Interleukin-10 (IL-10) is a key anti-inflammatory cytokine that regulates immune responses to prevent excessive tissue damage while maintaining control over infection." (PMID 40647525, 2025). "Three days after H9N2 infection, IL-1β, IL-6, and IL-10 were more significantly increased in all test groups than in the control group (p < 0.05)." (PMID 40218416, 2025). "Metastatic infection was positively correlated with increased IL-10 that trended towards significance in APMB compared to a negative correlation in ARMB." (PMID 39966757, 2025). "IL-6, TNF-α, IL-10 and other cytokines are important participating factors in the infection related cytokine storm." (PMID 40538651, 2025). "The results showed that there was an increase in TNF-α, IL-1β, and IL-10 production 24h after the infection by M. smegmatis (MOI 1:1) compared to the control group." (PMID 40142455, 2025). "Four-day carvacrol diet in secondary abiotic IL-10−/− mice prior C. jejuni infection reduced pathogen loads in their intestines at 6 days post-infection, and furthermore significantly alleviated acute enterocolitis symptoms." (PMID 40395728, 2025). "We observed that nine biomarkers (fractalkine, IFNγ, IL-5, IL-6, IL-10, IL-12, IL-13, IL-21, and TNFα) had significantly increased levels post-infection with subtype C HIV-1 compared to the pre-infection levels." (PMID 40862133, 2025). "In experimental infections with T. vivax in cattle and buffalo, a high presence of IFN-γ and TNF-α has been demonstrated, while in natural infections of cattle with T. vivax, the presence of IL-10 has also been detected, in addition to TNF-α." (PMID 40743218, 2025). "Plasma IL-10 progressively increased over the course of infection and peaked immediately prior to death, while TGF-β1 was significantly decreased at 5 DPC and 7 DPC compared to its peak at 1 DPC." (PMID 41156603, 2025). "Key findings include significant associations between polymorphisms in TLR4 (rs4986790), IL-10 (rs1800896), TNF-α (rs1800629), and MBL2 (rs1800450) with infection susceptibility, disease severity, and survival outcomes." (PMID 40692949, 2025). "Separately, this result further corresponded to significantly elevated IL-10 in APMB patients that succumbed to infection." (PMID 39966757, 2025). "Analyses of sera demonstrated elevated levels of the cytokines IL-6 and IL-10 in the in wild-type B6 mice compared to C3 knockout mice following infection with the Ig::Tn strain (respectively)." (PMID 40586810, 2025). "In the ITT (n = 105), when maternal blood was stimulated with P. aeruginosa, mimicking infection during pregnancy, IL‐10 levels were found to increase from mid‐pregnancy to late pregnancy in the intervention arm." (PMID 41369322, 2025). "A single intraperitoneal injection of MIP-1α and anti-IL-10 neutralizing antibodies abolished the survival protection of citrulline on day 3 post-infection." (PMID 39923847, 2025). "Our in vivo results showed that IL-20RA deficiency reduces the level of T cells expressing IL-10 and M2 macrophages but increases the levels of macrophages expressing IL-12 and IFN-γ and M1 macrophages in mice during infection." (PMID 41550952, 2025). "Last, our data demonstrate that the ability of fluoxetine to promote host adaptation to the infection and cooperative defenses is dependent on IL-10." (PMID 39951524, 2025). "The F3 vaccine, in contrast, absolutely prevented the increase of IL-10 after immunization and after infection, indicating that it induces a primary Th1 response." (PMID 40666521, 2025).
infection (continued). "Collectively, these findings underscore the critical role of IL-10 in preserving erythropoiesis during the acute stage of infection by controlling inflammation, particularly IFN-γ, and highlight the complexity of the inflammatory milieu in regulating EME." (PMID 41471231, 2025). "IFN-γ: activates macrophages; induces IL-6, TNF-α, IL-10 production via JAK-STAT; IFNγR1 deficiency increases infection susceptibility." (PMID 41268545, 2025). "IL-10 and its receptors are expressed in vertebrates, forming an ancient anti-infection mechanism that constitutes the inflammation resolution phase of host defense." (PMID 41312367, 2025). "In response to infection, neutrophils have been reported to produce the anti-inflammatory cytokine interleukin-10 (IL-10), both in humans and mice." (PMID 40943586, 2025). "While the precise mechanisms underpinning these altered responses to infection remain incompletely understood, prior work points to preferential expression of anti-inflammatory cytokines (such as IL-10) and evasion of innate immune sensing (RIG-I, TLR)." (PMID 39902963, 2025). "From the perspective of the color scale, the expressions of IL-8, IL-1β, IL-4, IL-6, IL-2, TNF-α, IL-10, and IL-17 showed a significant upward trend as the infection duration increased." (PMID 41165313, 2025). "IL-10 is a recognized anti-inflammatory factor that plays an important role in maintaining tissue homeostasis during infection and inflammation." (PMID 39926427, 2025). "Higher IL-4 and IL-10 levels seen at later time points following infection are likely correlated with this type of Th2 bias." (PMID 40704892, 2025). "Using a human cervical tissue explant model, we found that GC inoculation increased the local secretion of both proinflammatory (IL-1β and TNF-α) and antiinflammatory (IL-10) cytokines during the first 24 hours of infection." (PMID 39585777, 2024). "In summary, here, we found that S. anginosus triggers a proinflammatory response at 6 h post-infection yet induces production of IL-10 as well as a distinct extracellular metabolite profile as compared with untreated and S. mitis infection." (PMID 38289109, 2024). "An increase of both cytokines was observed for both infection doses compared to the control (IL-10: 7.75 pg/ml; TNF: 22.89 pg/ml)." (PMID 38979428, 2024). "IL-10, possessing anti-inflammatory properties, plays a pivotal role in infection by limiting immune responses to pathogens, thereby preventing damage to the host." (PMID 39654886, 2024). "There was a 3-fold defect in the frequency of CD69/CD103 double-positive cells among S- and N-specific CD4 T cells in the BAL at 4–5 weeks post-infection in the anti-IL-10 treatment group relative to controls." (PMID 38950078, 2024). "These immune cells are known to produce IL-10, particularly during the resolution phase of the infection, and also IL-6 and IL-27, which promote the maturation of Treg cells in the respiratory tract." (PMID 39595633, 2024). "At the same time, there is a predominance of the IL-6/IL-10 ratio, which likely indicates the severity of the infection." (PMID 38397914, 2024). "Upon measuring cytokine concentrations of 4 h and 24 h post-infection, IL-10 levels in mice treated with mAb 8E6 were significantly elevated at the initial stage of infection (4 h, p = 0.019) compared to those in mice that received isotype mAb treatment." (PMID 39460288, 2024). "In regard to Breg cell analysis, higher relative numbers of IL-10-producing B cells were found in A. lumbricoides infected subjects than in the NI group, mainly in those with stronger egg burden infection (p = 0.035)." (PMID 39312581, 2024). "In the uninfected sample, we observed that populations expressing IL-10 were more than IL-12-expressing cells, although we observed slight changes in depletion of IL-10-producing cells at 6 h of infection." (PMID 38299832, 2024).